CXCL12 (C-X-C motif chemokine ligand 12)
Diseases named in the same sentence as CXCL12 in open-access papers (continued):
Sharing a sentence is not in itself a finding about the gene and the disease.
tumor (continued). "CXCL10, CXCL5, MMP1, CXCL12, CXCL11, CXCL2, STAT1, IL‐6 and TLR2 were hub genes, which may drive the homing of immune cells in tumours and promote immune cell differentiation." (PMID 36524848, 2023). "ROS also initiated the inflammatory reaction by the NF-κB pathway to secrete chemokines both in tumor cells and the tumor microenvironment, such as CCL2, CCL3, CXCL2, and CXCl12, which were upregulated by Se-PC PDT, and CCL24 and CXC17, which were downregulated by Se-PC PDT in the tumor niche." (PMID 37994159, 2023). "Indeed, it has been suggested that tumor growth was associated with accumulation of regulatory B cells (Breg) within TDLNs, which in turn could promote cancer cells recruitment via the production of anti-HSPA4 immunoglobulin and the activation of the CXCL12/CXCR4 pathway." (PMID 38074683, 2023). "Stromal cell-derived factor-1 (SDF-1), also known as chemokine CXC ligand 12 (CXCL12), is expressed and secreted by a variety of cells including myeloid, endothelial, epithelial and tumor cells." (PMID 37153567, 2023). "Chemokines and their related receptors are another important hypoxic hotspot, which in turn affect tumor endothelial cells and increase the over expression of VEGF, CXCL12, and its receptor CXCR4, making all of them function on endothelial cells in an autocrine way." (PMID 37056346, 2023). "TGFBI, COL3A1, and CXCL12 were significantly upregulated in caf_C1_scissor, which mainly expressed genes characteristic of activated CAF, which secreted pro-inflammatory factors that enhanced EMT and stemness of tumor cells and contributed to tumor metastasis." (PMID 37091977, 2023). "CAFs typically secrete CXCL12, TGF-β, LOXL2, HGF, and IL-22 to promote tumor progression." (PMID 36992704, 2023). "Throughout brain development, microglia regulate a number of immune chemokines, such as CXCL12 and CXCR4, which could create a specific microenvironment for tumor cells to emerge." (PMID 37509316, 2023). "In renal cell carcinoma, IgA- and IgG-positive plasma cells derived from the TLS appear to disseminate into the tumor through CXCL-12-expressing fibroblast tracts, with TLS+ tumors exhibiting high frequencies of IgG-stained and apoptotic malignant cells, suggestive of anti-tumor effector activity." (PMID 36765578, 2023). "In glioblastoma cancer models, inhibition of the b-galactoside-binding lectin, galectin-1 has shown to enhance expression of CXCL10, CXCL12 and CCL5 resulting in recruitment of Gr-1+/CD11b+/CCR2+ myeloid cells which promoted the recruitment of tumor-infiltrating NK cells." (PMID 38022679, 2023). "Moreover, the EMT tumour cells can modulate the tumour microenvironment, and it is reported that the upregulation of SLUG increases the downstream expression of VEGFA and CXCL12 and promotes the angiogenesis." (PMID 37867401, 2023). "Normal fibroblasts do not produce mediators that stimulate angiogenesis, but tumor-associated fibroblasts generate bFGF, PDGF, and CXCL12 in addition to VEGF, which further support tumor neoangiogenesis." (PMID 38139365, 2023). "Multiple proinflammatory/immune recruitment (IL-1β, IL-6, IL-8, TNFα, IFNα, MIP-1β, CXCL12) and immune suppressive cytokines (IL-10) were found to be induced by tumor line-derived sEVs but not those derived from normal pancreatic cell lines." (PMID 37834100, 2023). "It seems reasonable, but not yet proven, that CXCL12•HMGB1 complexes influence tumor cell migration and metastasis." (PMID 37446102, 2023). "It has been reported that high CXCL12 levels in GBM may attract CXCR4-positive vascular and inflammatory cells such as TAMs that, once within the tumor, secrete tumor-promoting cytokines as well as growth and pro-angiogenic factors." (PMID 37190507, 2023). "OPN could facilitate the transformation of mesenchymal stromal cells into CAFs, as well as increasing levels of CAF markers such as α-SMA, CXCL12, FSP-1, and tenascin-c specifically at tumor metastatic sites." (PMID 37496657, 2023).
tumor (continued). "As the dipeptidyl peptidase CD26 is associated with inactivation of CXCL12, absent or lower CD26 expression and activity in the tumor can result in a defective truncation and prolonged activity of CXCL12." (PMID 36725964, 2023). "CXCL12 is pivotal in the initial stages of tumorigenesis, and studies have corroborated that fibroblast-derived CXCL12 consumption mitigates tumor cell proliferation while recruiting endothelial progenitor cells to the TME, thus expanding tumor vessels." (PMID 38001753, 2023). "Moreover, nonmutant fibroblasts have the potential to increase the proliferation of mutant desmoid tumor cells by secreting soluble factors that include PTX3, CCL2, and CXCL12." (PMID 37377751, 2023). "These infiltrated immune cells and solid tumor cells release tumor-progressing cytokines (IL-6, TNF-α, TGF-β), chemokines (CCL2, CCL5, CCL18, CXCL8, CXCL12), and growth factors (EGF, PGF, IGF-1, IGF-2, PDGF) that promote tumor microenvironment immunosuppressive." (PMID 37371075, 2023). "Notably, CXCR4/CXCL12 cross-signal via the T and B cell receptors (TCR and BCR) and co-internalize with CD47, promoting tumor cell phagocytosis by macrophages in an anti-tumor immune process called ImmunoGenic Surrender (IGS)." (PMID 35565443, 2022). "In support of this, in mouse lung cancer, also IL-33 was related to good prognosis since it could elevate the frequency of tumour infiltrating ILC2s via CCL5, CXCL10, and CXCL12." (PMID 35406451, 2022). "There were no pronounced differences in the VEGF and CXCL12 secreted levels between the tumours of different ATF4 host status." (PMID 35654839, 2022). "High CXCL12 in the TME thus provides paracrine signaling via a feedback loop that mediates integrin b1 clustering at the tumor cell surface, promotes tumor EMT and prevents apoptosis via upregulated CXCR4 on tumor cells." (PMID 36244987, 2022). "Additionally, we acquired a total of 6 molecules including IL6, AREG, CXCL12, TGFβ, VEGF and CCL2, which can be upregulated upon senescence, influence immune cell functions, and play tumor-promoting roles in TME30." (PMID 35361903, 2022). "The CXCL12 chemokine mediated pro-angiogenic and prometastatic effects through receptors CXCR4 and CXCR7, while the neutralization of this chemokine reduced the angiogenic potential of the tumor." (PMID 36354566, 2022). "The transcriptional levels of 5 chemokines (CXCR5, CXCL12, CXCL13, CCL19, and CCL21) that have been reported to be involved in the formation of TLSs were also prominently elevated in both the tumor specimens from mIgG2c-G400R mice and hIgG1-G396R homozygous CRC patients." (PMID 35133976, 2022). "We further wish to note that although in none of our tumor cells CXCL12-induced cell migration was sensitive to SB203580 this does not imply that the CXCL12-p38-axis is not involved in the control of cell migration." (PMID 36539774, 2022). "CXCL12-abundant reticular (CAR) cells are encapsulated around or located in the vicinity of sinusoidal endothelial cells and appear to be a key component of the osseous niche that provides a protective barrier to tumor cells." (PMID 36497209, 2022). "Since, higher expression of CXCL12 was linked with a positive ER status, a negative HER2 status, and a small tumor size, this confirms the role of CXCL12 as a favorable prognostic factor." (PMID 35203510, 2022). "Furthermore, hypoxia/HIF-1α induces the secretion of CXCL12, VEGF, and ANG1/2, leading to vascular changes, such as fragile tumor angiogenesis, through the recruitment of vascular endothelial cells." (PMID 35743281, 2022). "Importantly, TGFβ can serve as a central node to mediate CAF function by cross-regulating multiple signaling pathways to support tumor growth, including PI3K/AKT, CXCL12, FGF, and Wnt/β-catenin cascades." (PMID 36671452, 2022). "Since many tumors show increased expression of both CXCL12 and CXCL11, we now asked whether CXCL12 and CXCL11 would exert combined effects on tumor progression." (PMID 36539774, 2022).
tumor (continued). "CAFs secrete various soluble ligands such as CXCL12, CCL7, and TGF-β, which may interact with tumor cells and promote tumor progression." (PMID 35953863, 2022). "Despite CAF-secreted CXCL12 promoting tumor-like vasculature, CXCL12 does not appear to control fibroblast contractility through upstream autocrine signaling mechanisms." (PMID 36118583, 2022). "We showed that TAb2 tumor cells expressed higher levels of CSF1, VEGF, HGF and CXCL12." (PMID 35366939, 2022). "The divergent responses are not the result of the distinct use of different CXCL12- and CXCL11-receptors by the respective tumor cells, but in case of cell migration seem to be associated with the activation of p38 signaling pathways." (PMID 36539774, 2022). "At present, some researchers have confirmed that after PC saponin administration, serum IL-6 and TNF-α levels, expression of VEGF and CD31 in liver tissues, and CXCR4, CXCL12, MMP-9 and MMP-2 proteins in spleen tumor tissues of colon cancer mice were significantly reduced." (PMID 35814470, 2022). "Bone-homing tumor cells tend to overexpress chemokine receptors, CXCR4, CXCR6, and CXCR2 that subsequently contribute to the movement of the tumor cells from the bone marrow to other organs by seeking CXCL12, CXCL-16, and CXCL-10 respectively." (PMID 35399952, 2022). "The interacting of CXCL12 and CXCR4 could activate divergent intracellular pathways related to chemotaxis, cell proliferation and gene transcription in tumor development." (PMID 36387901, 2022). "Interestingly, one study showed that activated PSCs secrete C-X-C motif chemokine ligand 12 (CXCL12) to sequester CD8+ T cells, reducing CD8+ T-cell infiltration in the juxtatumoural compartment (identified as <100 μm from the tumour)." (PMID 36299300, 2022). "Numerous cytokines and chemokines known to enhance stromal activity such as TGFB1, TGFB2, TGFB3, CXCL12, CCL2 and IL-6 were found downregulated in 211F MEF cells, suggesting a potential tumor-promoting function of Y211 phosphorylation through regulation of the secretome in the stromal environment." (PMID 35628489, 2022). "In contrast, no CXCL12 gradient was observed between homogenates of non-tumor tissues and plasmas (P = 0.578)." (PMID 35941662, 2022). "In this context, the CXCL12/CXCR4 axis plays a decisive role in the development and progression of cancer, including cell proliferation and metastasis, tumor angiogenesis, the epithelial mesenchymal transition, intracellular calcium increase, and gene transcription." (PMID 35893797, 2022). "In gastric cancer cells, CXCL12/CXCR4 signaling can activate NF-kB; this upregulates the expression of serine protease inhibitor branch B member 3 (SERPINB3), thus promoting the metastasis of tumor cells." (PMID 35893797, 2022). "Tumor-derived factors such as colony-stimulating factor 1 (CSF1; also known as M-CSF), granulocyte-macrophage colony-stimulating factor (GM-CSF), CC-chemokine ligand 2 (CCL2), CCL7 (or MCP-3), GDNF, IL-33, CXCL12 (SDF-1) and EGF are responsible for myeloid cell recruitment and promote tumor growth." (PMID 36140392, 2022). "The CXCL12 and CXCR4 tumor expression positively correlated (Spearman’s r = 0.42, p = 0.004)." (PMID 36359736, 2022). "In addition, CXCL12 and CXCR4 are involved in antigen recognition by T and B cells and in shaping the tumor microenvironment (TME), mainly towards dampening immune responses." (PMID 35565443, 2022). "There have been specific studies about CXCL12 and CXCL14 in CAFs in tumor progression." (PMID 36119108, 2022). "We have now analyzed CXCL12 and CXCL11 for combined effects on tumor progression." (PMID 36539774, 2022). "Interestingly, among patients with radical resection (R0), high tumor CXCR4 clustered patients with worse RFS, high CXCL12 identified poor prognostic patients for both RFS and CSS, while stromal lymphocytic-monocytic PD-L1 associated with improved RFS and CSS." (PMID 36359736, 2022).
tumor (continued). "In addition, the interaction between CXCL12 and its receptor CXCR4 has generated widespread interest with regard to tumor progression." (PMID 35893797, 2022). "In addition, HSCs, together with liver sinusoidal endothelial cells, are one of the principal sources of CXCL12 secretion in the liver, where they mediate not only the recruitment of CXCR4-expressing tumor cells, but also of CXCR4-expressing immune cells." (PMID 35406582, 2022). "TAMs originate from peripheral blood monocytes that infiltrate into the tumor microenvironment in response to cytokines such as VEGF, colony stimulating factor-1 (CSF1), CXC motif chemokine ligand-12 (CXCL12) and various CC motif chemokine ligands (CCL) such as CCL2." (PMID 36421358, 2022). "CXCL12, another chemokine secreted by osteoblasts, triggers DTC dormancy in the bone marrow by binding to C-X-C motif chemokine receptor 4 (CXCR4), one of the receptors of CXCL12 in tumour cells." (PMID 36307871, 2022). "Another important study has demonstrated that tumor-infiltrating MDSCs usually are CXCR4 positive and could migrate toward the CXCL12 gradient." (PMID 34980128, 2022). "Similarly, targeting CXCL12 induced rapid T-cell accumulation among PDAC cancer cells and acted synergistically with anti-PDL1 immunotherapy to reduce tumour burden in murine PDAC." (PMID 36358721, 2022). "In the intraperitoneal metastatic microenvironment, CAFs govern the metastatic cascade, including the adhesion, proliferation, invasion, and colonization of metastatic sites via increasing production of several molecules (CXCL12, IL-6, VEGFA, TGF-α, and β, FGF-1) within the tumor microenvironment." (PMID 35216340, 2022). "These factors include chemokines, cytokines and growth factors, such as the vascular endothelial growth factor (VEGF), CXCL12 and CXCL14, and interleukins (ILs) IL-6 and IL-17A, which are critical for tumour cell proliferation, angiogenesis, invasion, inflammation, metastasis and drug resistance." (PMID 36140541, 2022). "In addition, tumor hypoxia induces the expression of CCL28, CXCL12 and CXCR4, selectively enhanced the recruitment of T(reg) cells, thereby inducing tumor tolerance and new angiogenesis." (PMID 36226050, 2022). "Interestingly, CXCL12 neutralization by NOX-A12 chemosensitizes CLL, MM, and CML cells resulting in their reduced survival in vitro or tumor burden in vivo." (PMID 36568151, 2022). "Many cytokines secreted by tumor cells can recruit macrophages to the TME, but some of them are exclusively produced by CSCs: CCL2, CCL3, CCL5, CXC motif chemokine ligand 12 (CXCL12), olfactomedin-like 3 (OLFML3), stromal-cell-derived factor-1b (Sdf1b), IL-6, IL-33, and CSF-1." (PMID 35740975, 2022). "To assess whether the combined effects of CXCL12 and CXCL11 on tumor cell invasion involve MMPs as an intermediate, we focused on the gelatinases MMP-2 and MMP-9, which represent known targets of CXCL12 and CXCL11." (PMID 36539774, 2022). "Our findings indicate that fibroblast-secreted CXCL12 has a significant role in promoting a leakier endothelium hospitable to angiogenesis and tumor cell intravasation; however, autocrine CXCL12 is not the primary upstream trigger of CAF contractility." (PMID 36118583, 2022). "The existence of such combined influences is nevertheless likely and might eventually render further complexity to the crosstalk of CXCL12 and CXCL11 in tumor progression." (PMID 36539774, 2022). "Additional in vitro experiments demonstrated that activated B cells provoked direct cytotoxic action on tumor cells through CXCR4/CXCL12 pathways, while without cell contact, B cell-secreted perforin also led to tumor cell cytotoxicity." (PMID 35967441, 2022). "Stromal cell-derived factor-1 (SDF-1), also known as CXC motif chemokine ligand-12 (CXCL12), which binds to the CXC receptors 4 and 7, is ubiquitously expressed in almost all organs and involved in several aspects of tumor progression, including angiogenesis, metastasis, and survival." (PMID 36341391, 2022).
tumor (continued). "In addition, through PI3K/AKT signaling, CXCL12 and its specific receptor CXCR4 have been shown to increase VEGF synthesis mediated by GSCs and tumor angiogenesis." (PMID 35269652, 2022). "The results showed that TTCS induced significantly more tumor‐infiltrating neutrophils to migrate than NTCS from the same GC patients, and such migration was blocked upon pre‐treatment with neutralizing antibodies against CXCL12 and/or CXCR4." (PMID 34957697, 2022). "CAF is an abundant source of VEGFA and other pro-angiogenetic factors such as platelet-derived growth factor C (PDGFC), fibroblast growth factor 2 (FGF-2), and C-X-C motif chemokine 12 (CXCL12/SDF-1), which directly or indirectly regulates tumor neovascularization." (PMID 35327514, 2022). "CXCL12, the sole chemokine ligand for CXCR4, was abundant in 6 out of 12 supernatants from the GNS cell cultures, however it was undetectable in all dissociated tumour biopsy and CUSA samples analysed." (PMID 35464424, 2022). "We found less tumor control in mice treated with anti-CXCL12 than with IgG (control) in the setting of 7HP349, but not vehicle." (PMID 35552271, 2022). "Previous research indicated an involvement of the SDF-1/CXCL12–CXCR4 axis in tumorigenesis and metastatic progression by enhancing tumor cell migration towards the liver along a CXCL12 gradient, as well as by inhibiting tumor cell and CD8+ T-cell interaction in the TME." (PMID 35740692, 2022). "In addition to their direct effects on tumor cell function, CXCL12 and CXCL11 indirectly control tumor progression by modulating the tumor microenvironment, thereby affecting immune responses and tumor angiogenesis." (PMID 36539774, 2022). "Tumor cells have high concentrations of CXCL12 suspected to be due to the overexpression of high mobility group box 1 (HMGB1), an overexpressed protein by metabolically stressed cancer cells that captures CXCL12." (PMID 35844304, 2022). "Another study found that CXCL12, which FAP+ CAFs secrete, inhibits the accumulation of cytotoxic T cells in the vicinity of the tumour and may direct tumour immune evasion in a human PDAC model." (PMID 36284087, 2022). "The CXCL12/CXCR4 axis is a classic signaling that governs the homing of MSCs and upregulates the expression of PD-L1 to mediate selective immunosuppression within a tumor." (PMID 36324128, 2022). "CXCL12 was found to be critical in enhancing the GM-CSF/Heparin-binding epidermal growth factor (HB-EGF) paracrine loop of colon cancer metastases in the liver, advancing tumor anti-apoptosis and the recruitment of TAMs." (PMID 36311793, 2022). "EPCs lead to tumor progression through increasing production of VEGF-A, CXCL12, or CXCR4." (PMID 35203510, 2022). "For example, the chemoattractant CXCL12, by binding to its CXCR4 receptor, activates signaling pathways that play a critical role in tumor progression and invasion, making it an interesting therapeutic target to properly control the direction of GBM cell migration for treatment proposes." (PMID 35745762, 2022). "CXCL12 recruits CXCR4+ BMDCs to the tumour, including vascular progenitor cells that can differentiate and incorporate into new blood vessels, but also MMP-9-expressing myeloid cells that indirectly regulate tumour angiogenesis." (PMID 33803414, 2021). "In the therapeutic model, upon animal sacrifice, the tumor masses were excised and subjected to qRT-PCR analysis of the human and mouse genes in order to assess the effects of the RGZ and MTT in vivo treatment on the CXCL12/CXCR4/CXCR7 axis and tumor vascularization." (PMID 34834449, 2021). "These inflammatory CAFs release factors, such as TGFβ-1, C-X-C motif chemokine ligand 12 (CXCL12), PDGF and IL-6, that enhanced tumor cell dispersion, scattering, and migration, by stimulating the chemokine receptors CCR2, CCR5, and CXCR1/2 and Ras-activating receptors, expressed by BC cells." (PMID 34885027, 2021). "Multiple tumor cell rely on CXCR4 and its ligand, SDF-1/CXCL12, to metastasis." (PMID 34220311, 2021).